ASXL1 (ASXL transcriptional regulator 1)
Diseases named in the same sentence as ASXL1 in open-access papers (continued):
Sharing a sentence is not in itself a finding about the gene and the disease.
myeloid malignancies (continued). "Mutant ASXL1 is frequently present in different myeloid malignancies, namely MDS, myeloproliferative neoplasms (MPNs), MDS/ MPNs, and primary and secondary AML." (PMID 38807730, 2024). "In myeloid neoplasms, EZH2 mutations tend to be mutually exclusive with SRSF2 and U2AF1 mutations, while it is more frequently co-mutated with ASXL1 and TET2." (PMID 38673842, 2024). "Some investigations reported the co-occurrence of ASXL1 mutations with EZH2, IDH1/2, RUNX1, and TET2 in myeloid malignancies." (PMID 38807730, 2024). "The majority of ASXL1-mutated patients had other concurrent gene mutations, and splicing factors (SRSF2, U2AF1, ZRZR2, SF3B1) were most frequently mutated in myeloid malignancies." (PMID 38017104, 2024). "Importantly, inhibition of KDM6B restored H3K27me3 levels in Asxl1Y588XTg Kdm6bΔ/+ BM cells, prompting us to initiate preclinical studies to determine whether targeting KDM6B could potentially benefit patients with ASXL1 mutation–associated myeloid malignancies." (PMID 37917239, 2024). "Our study indicated that MDS/MPN is characterized by mutations commonly identified in myeloid neoplasms, with TET2 (52%) being the most frequently mutated gene, followed by ASXL1 (38.7%), SRSF2 (34.7%), and JAK2 (19.7%), among others." (PMID 39337700, 2024). "To understand the role of functional immune system in AML progression, we have used several mouse myeloid tumor models driven by MLL-AF9, RUNX1-ETO9a, ASXL1/RUNX1 mutations and ASXL1/SETBP1 mutations." (PMID 38129572, 2023). "Of note, ARCH is characterized by the presence of somatic mutations in genes that are also frequently mutated in SM (e.g., ASXL1, DNMT3A, EZH2, RUNX1, SF3B1, SRSF2 and TET2) and other myeloid neoplasms." (PMID 35626091, 2022). "Recent studies have revealed that somatic mutations are detected in approximately 30% of AA patients, and mutations in several genes such as DNMT3A, ASXL1, and RUNX1 are associated with secondary myeloid malignancies." (PMID 36467821, 2022). "It has also been shown that mutant ASXL1 disrupts the function of PRC1 and causes derepression of expression in target genes, which possibly leads to the development of myeloid malignancies, including MDS." (PMID 35821550, 2022). "An additional four CHIP genes (ASXL1, TET2, JAK2, and DDX41) were significantly associated with myeloid neoplasms and are likely driven by somatic alterations." (PMID 36199081, 2022). "We applied the superRCA assay for the GC-rich ASXL1 p.G646fs*12 mutation, previously detected by NGS in samples collected from four patients with myeloid malignancies (AML or MDS)." (PMID 35821208, 2022). "We generated an endogenous C-terminal-truncated Asxl1 mutant in zebrafish that mimics human myeloid malignancies." (PMID 33483612, 2021). "Patients with multiple myeloid malignancies including MDS, CMML, and AML frequently harbor somatic mutations in addition of sex combs-like 1 (ASXL1)." (PMID 33483612, 2021). "Functionally, ASXL1 is required to suppress abnormal expression of HOX genes and ASXL1 is frequently mutated in myeloid malignancies." (PMID 35201498, 2021).
myeloid malignancies (continued). "Whole-exome sequencing analyses revealed a 2.9% ASXL1 is mutation rate in CLL, with generally higher percentages in myeloid neoplasms (45.3% in CMML, 34.5% in MPN, 30% in secondary AML, 16.2% in MDS, and 6.5% in de novo AMLs)." (PMID 34947882, 2021). "A share of TN MPNs discloses variants of myeloid neoplasm-/CHIP-associated genes (i.e., DNMT3A, TET2, and ASXL1) with ascertained or putative pathogenicity." (PMID 34830822, 2021). "Next-generation sequencing (NGS) is used to detect and monitor clonal hematopoiesis, and the spectrum of mutations substantially overlaps with that of myeloid neoplasms with DNMT3A, TET2, ASXL1, and JAK2 being the most frequently mutated." (PMID 32825226, 2020). "A transgenic mouse model that expresses a truncated Asxl1 protein exhibited a gain-of-function alteration and induced myeloid malignancies." (PMID 31064769, 2019). "Each SF is also associated with a distinct pattern of mutations in other genes commonly detected in myeloid malignancies, as in the case of SRSF2 mutations with TET2 mutations in CMML and with RUNX1, IDH2, and ASXL1 mutations in AML." (PMID 31766606, 2019). "The disease was transplantable, with a shorter latency for myeloid malignancies with Asxl1 null hematopoietic cells versus those with haploinsufficiency." (PMID 31064769, 2019). "ASXL1 c.1934dupG; p.Gly646fs was found in diverse groups of myeloid neoplasms (MDS, MDS/MPN, AML and MPN) in this study and across all age groups (median, 70 years; range 54–85 years)." (PMID 30222780, 2018). "Clinical data revealed frequent coexistence of ASXL1 and SETBP1 mutations in myeloid neoplasms, and we previously demonstrated their cooperation to promote leukaemic transformation in mouse MDS/AML models." (PMID 30367089, 2018). "These were twice combined with additional mutations, including TET2 and SRSF2 mutations in a CMML case, and ASXL1, TET2, and U2AF1 mutations in the disseminated case of an undefined myeloid neoplasm accompanied by HLH (case 10)." (PMID 30084011, 2018). "Future work is warranted to decipher this critical question and unveil the roles of ASXL1 and ASXL2 mutations in the pathogenesis of myeloid malignancies." (PMID 28593990, 2017). "Additional sex combs-like 1 (ASXL1) is the human homolog of Drosophila additional sex combs (Asx), frequently mutated in acute myeloid leukemia (AML) and other myeloid malignancies." (PMID 28697759, 2017). "We also observed a high frequency of ASXL1, SETBP1 and SRSF2 mutations in myeloid neoplasms associated with i(17q)." (PMID 26883102, 2016). "Clonal hematopoiesis of indeterminate potential (CHIP) serves as a critical precursor to leukemogenesis, characterized by recurrent mutations—most frequently in DNMT3A, TET2, and ASXL1—that emerge in otherwise healthy individuals and significantly elevate the risk of AML and other myeloid neoplasms." (PMID 41451201, 2025). "Several studies have highlighted co-mutation of ASXL1 and SRSF2 in subsets of myeloid neoplasms, for which the clinical implications remain unclear." (PMID 40562788, 2025). "CNL can also arise from different myeloid neoplasms; a recent case report showed a patient who was diagnosed with MDS with U2AF1 and SETBP1 mutations who, 3 years later, developed CNL and acquired CSF3R and ASXL1 mutations." (PMID 39858009, 2025). "Notably, the application of GSK-J4 inhibits the mutant ASXL1–mediated leukemic cell growth and prevents the development of mutant ASXL1–driven myeloid malignancies." (PMID 37917239, 2024). "In addition to their roles in myeloid malignancies, deletion studies in mice have shown that both Asxl1 and Asxl2 regulate hematopoiesis, whereas the role of Asxl3 in hematopoiesis remains unexplored." (PMID 38791157, 2024).
myeloid malignancies (continued). "The data we have presented herein demonstrate that heterozygous deletion of Kdm6b blocks the development of ASXL1 mutation–mediated myeloid malignancies, and that the KDM6B inhibitor GSK-J4 likewise attenuates ASXL1-mutated leukemic cell growth and tumor burden in preclinical mouse models." (PMID 37917239, 2024). "ASXL1 loss or mutation impairs the recruitment of PRC2 complex proteins to chromatin, reducing H3K27me3 deposition, and leading to associated leukemogenic gene dysregulation and the development of myeloid malignancies." (PMID 37917239, 2024). "For example, our group recently demonstrated that frameshift mutations affecting the BAP1 complex subunit ASXL1 (which are frequently observed in myeloid malignancies) create truncated gain-of-function ASXL1 mutants that stabilize the BAP1 complex and increase its recruitment to chromatin." (PMID 39403928, 2024). "Most ASXL1 mutations in myeloid malignancies are frameshift or nonsense mutations in exon 12 (last exon) before the PHD finger, enabling the resulting mutant mRNA to escape nonsense-mediated decay and generate a stable C-terminal truncated ASXL1." (PMID 36068610, 2022). "Loss of Asxl1 was reported to lead to MDS-like disease in mice, whereas enforced overexpression of truncated forms of ASXL1 show gain-of-function and promote the pathogenesis of myeloid malignancies." (PMID 31405121, 2019). "In addition, genes involved in histone methylation and demethylation, for example ASXL1, EZH2, and DOT1L are frequently mutated in myeloid malignancies." (PMID 31405121, 2019). "Additional sex combs-like 1 (ASXL1) mutations have been described in all forms of myeloid neoplasms including chronic myelomonocytic leukemia (CMML) and associated with inferior outcomes, yet the molecular pathogenesis of ASXL1 mutations (ASXL1-MT) remains poorly understood." (PMID 31640815, 2019). "We argued that deletion of Asxl1 in the BM niche could cooperate with Asxl1-null HSC/HPCs to accelerate the pathogenesis of myeloid malignancies in vivo." (PMID 29423272, 2018). "Our study provides a further mechanistic insight into ASXL1 functions in the BM niche, and how ASXL1 alteration-associated defective niche works in concert with an intrinsic effect of ASXL1 alteration-mediated HSC/HPC defects to promote the pathogenesis of myeloid malignancies." (PMID 29423272, 2018). "OGT can induce the differentiation of MDS/AML cells in vitro and extend the survival rate of mice carrying leukemic cells expressing mutant ASXL1, which occurs at high frequencies in myeloid malignancies, by conjugating O-GlcNAc to ASXL1-S199 and thereby stabilizing this tumor suppressor protein." (PMID 30237983, 2018). "The presence of genetic abnormalities in genes related to the development of myeloid neoplasms in aging population (e.g., JAK2, DNMT3, TET2, and ASXL1) is associated with increased risk of hematologic malignancies, all-cause mortality, and cardiovascular disease." (PMID 30056580, 2018). "Future efforts are warranted to investigate if ASXL1 mutation/dysregulation in the BM niche of patients contributes to the pathogenesis of myeloid malignancies, which will shed light on identifying novel therapeutic strategies for patients with ASXL1 alterations." (PMID 29423272, 2018). "Therefore, reducing BAP1 levels and activity could prevent ASXL1 truncation-driven myeloid malignancies." (PMID 35194152, 2022).
myeloid malignancies (continued). "In addition, we reported that ASXL1 truncation mutations enhanced BAP1 deubiquitinase (DUB) activity, and that genetically reducing BAP1 in Asxl1Y588XTg mice prevented the development of myeloid malignancies." (PMID 36068610, 2022). "Of note, ASXL1 mutations are frequently seen with other gene alterations, such as with EZH2 IDH1/2, RUNX1, and TET2, most of which are adverse prognostic factors themselves in myeloid neoplasms, potentially explaining why ASXL1 mutations are associated with poor prognosis in many cases." (PMID 34947882, 2021). "However, C-terminally truncated forms of Asxl1 that are similar to the most abundant ASXL1 mutations occurring in CHIP and myeloid malignancies, produce different effects, namely enlarged hematopoietic stem cell (HSC) pool and increased susceptibility to leukemic transformation." (PMID 33114351, 2020). "Given the fact that global deletion of Asxl1 results in biased myeloid differentiation, we questioned that Asxl1-deficient niche may alter the cell fates of HSC/HPCs, contributing to the pathogenesis of myeloid malignancies." (PMID 29423272, 2018). "Around 60% of CD34+ cells from patient 2 [P2(h)] exhibited a heterozygous JAK2V617F mutation (JAK2V617F/WT) whereas no mutation was identified in these cells in ASXL1 and the other genes involved in myeloid malignancies, including TET2, EZH2, DNMT3A, IDH1 and SRSF2." (PMID 24066127, 2013). "Importantly, the addition of GSK-J4 significantly inhibited colony formation from primary cells of myeloid malignancy patients with ASXL1 mutations, whereas a minimal effect of GSK-J4 was observed in the primary cells of a myeloid malignancy patient without ASXL1 mutation." (PMID 37917239, 2024). "TET2 mutations have been observed to co-occur with NPM1, FLT3-ITD, JAK2, ASXL1, calreticulin (CALR), SF3B1 and RUNX1 revealing the range of epigenetic connections to cellular processes amongst various myeloid malignancies." (PMID 34065087, 2021). "Thus, haploinsufficiency for ASXL1, the main acquired genetic abnormality in human myeloid malignancies, does not by itself seem to reproducibly induce hematopoietic malignancies in mice." (PMID 31064769, 2019). "For example, microhomology-mediated recurrent deletions of CALR, ASXL1, and SRSF2 and non-recurrent deletions in TET2, DNMT3a, CEBPA, and RUNX1 have been reported in myeloid neoplasms." (PMID 36011278, 2022).
leukemia (88 papers, 2012 to 2025). A malignant (clonal) hematologic disorder, involving hematopoietic stem cells and characterized by the presence of primitive or atypical myeloid or lymphoid cells in the bone marrow and the blood. "Another patient with R/R ASXL1-mutated MDS/AML achieved morphologic leukemia-free state (MLFS) after one cycle, but cytopenias persisted across two cycles." (PMID 41199910, 2025). "The DNMT3A mutation results in the accumulation of cells in the bone marrow due to impaired differentiation, while ASXL1 is crucial in the pathogenesis of leukemia by altering histone modifications and increasing the risk of transformation to MDS." (PMID 39873798, 2025). "To gain insight into the impact of KDM6B overexpression in truncated ASXL1–associated leukemia development, we generated two KDM6B knockout clones in K562 cells using the CRISPR/Cas9 system." (PMID 37917239, 2024). "In vivo studies corroborate iBAP's efficacy, showing delayed progression in leukemia and improved survival in mice models bearing ASXL1 mutations." (PMID 39678489, 2024). "Research shows that leukemia cells harboring truncated ASXL1 gain‐of‐function mutations, such as K562 cells and THP1 cells, are particularly sensitive to iBAP treatment." (PMID 39678489, 2024). "This discrepancy suggests a more pronounced effect of ASXL1 mutations on gene regulation within the context of leukemia." (PMID 39614348, 2024). "In AML, where ASXL1 variants are only in the leukemia stem cells (LSCs), there is a potential imbalance in paracrine signaling factors and receptors between the microenvironment (no ASXL1 variant) and the LSC (with ASXL1 variant)." (PMID 39614348, 2024). "We next performed Western blots to assess the protein levels of KDM6B in two leukemia cell lines, Kasumi-1 and K562 cells with ASXL1 truncating mutations as ASXL1 G646WfsX12 and ASXL1 Y591X, respectively." (PMID 37917239, 2024). "DNMT3A, TET2, and ASXL1 (“DTA”) mutations prevalently occur early in pre-leukemia hematopoietic stem and progenitor cells (HSPCs), persist for a long time and are not considered to be associated with poor prognosis." (PMID 35865470, 2022). "A closer look into the mutations that persisted following therapy (at remission) in responders revealed that they were in genes associated with pre‐leukaemia (ASXL1, DNMT3A, IDH2, SRSF2 and TET2)." (PMID 36051087, 2022). "For instance, hyper-activation of BAP1 induced by ASXL1 gain-of-function mutations has been demonstrated to be drivers in leukemia of an animal model." (PMID 35194152, 2022). "Deposition of 6 mA by Mettl4 also triggers proteolytic destruction of sensor proteins (e.g., ASXL1) that have been linked to multiple cancers, including leukemia and glioblastoma." (PMID 35177638, 2022). "In this study, we explore the molecular and cellular effects of genetic deletion of mutant ASXL1 allele in the context of other collaborating oncogenic alterations in leukemia cell lines." (PMID 32683582, 2021). "The leukemia cell lines K562 and Kasumi-1 harbor endogenous ASXL1 mutations, generating a nonsense mutation Y591X and a frameshift mutation G646Wfs*12, leading to the premature termination of ASXL1 protein at codon 590 and 646, respectively." (PMID 32683582, 2021). "In contrast, CRISPR/Cas9-mediated correction of ASXL1-truncated mutation decreases the proliferation of corresponding leukemia cells." (PMID 33796551, 2021). "A previous study showed that RUNX1 mutation promotes leukemogenesis of myeloid malignancies in ASXL1+ leukemia and is associated with adverse prognoses of patients with de novo AML." (PMID 34627254, 2021).